MIF (macrophage migration inhibitory factor)
Diseases named in the same sentence as MIF in open-access papers (continued):
Sharing a sentence is not in itself a finding about the gene and the disease.
glioma (67 papers, 2009 to 2025). A benign or malignant brain and spinal cord tumor that arises from glial cells (astrocytes, oligodendrocytes, ependymal cells). "The MIF signaling axis on CD74/CXCR4 was found to be upregulated in glioma infiltrating macrophages and has been implicated in brain tumorigenesis by impeding microglial polarization." (PMID 38515213, 2024). "Other Authors have reported that stable knockdown of MIF by shRNA in glioma cells increased tumour cell susceptibility towards NK cell- and CD8+T cell- mediated cytotoxicity by downregulating the immune receptor NKG2D on NK and CD8+ T cells." (PMID 29707160, 2018). "In glioma specimens, we found that VM formation was closely associated with high co-expression of MIF and CXCR4." (PMID 29113309, 2017). "Several genes are able to recruit neutrophils, in particular immunosuppressive neutrophils at the tumor site, such as IL8 which produced by glioma cells, factor associate suicide ligand (FasL) which was triggering, and MIF which was produced by glioma cancer stem cells." (PMID 37322408, 2023). "Our findings showed that the inhibition of the up-regulated MIF signaling cascade in glioma renders tumor cells susceptible to apoptosis, and which suggests that it may also promote radiation-induced apoptosis, thereby contributing to radio-sensitization." (PMID 34516577, 2021). "One recent study showed that reduced MIF expression was observed in bevacizumab-resistant glioma cells, which in turn was associated with increased M2-like TAM recruitment and the promotion of tumor progression and further resistance to anti-angiogenic treatment." (PMID 31366997, 2019). "Of these, MIF was of particular interest as it has been implicated in MDSC development previously but its role in glioma-induced MDSC accumulation is unknown." (PMID 28666020, 2017). "Glioma stem cells activate MDSCs by secreting macrophage migration inhibitory factor (MIF), thereby suppressing immune responses." (PMID 41368628, 2025). "Upregulation of metalloproteinase inhibitor 3 (TIMP3) and inhibition of the PI3K/ACT signalling pathway and knockdown of MIF resulted in a significant increase in susceptivity of drug‐resistant glioma cells to TMZ." (PMID 39950738, 2025). "In our study, we found that EIF3J-AS1 overexpression inhibits autophagy in glioma cells by increasing MIF expression, thereby promoting glioma progression." (PMID 41390674, 2025). "Mechanistically, METTL3 induced the generation of LINC00475-S by splicing LINC00475 through m6A modification and subsequently promotes mitochondrial fission in glioma cells by inhibiting the expression of MIF." (PMID 38405130, 2024). "Blockade of MIF by shRNA in glioma cells restores cytotoxic activity of NK and CD8 + T cells downregulating the immune receptor NKG2D." (PMID 38178143, 2024). "Meanwhile, MIF affects macrophages/microglia, promoting an M2 immunosuppressive state, which contributes to a tumor immunosuppressive microenvironment and hinders glioma immunity." (PMID 38348047, 2024). "Exosome-mediated transport of MIF has been shown to suppress temozolomide resistance in gliomas by modulating the TIMP3/phosphatidylinositol 3-kinase (PI3K)/AKT signaling axis." (PMID 38405130, 2024). "Blockade of MIF by miR-608 in glioma stem cells reduced the proliferation, translocation, and invasion." (PMID 38178143, 2024). "The MIF signals sent by glioma cells (Clusters C1, C2 and C4) were mainly received by TAMs (Cluster C0) via receptors CD74 and CXCR4, and by lymphocytes (Cluster C6) via CD74, CXCR4 and CD44." (PMID 38515213, 2024). "Monoclonal antibodies against MIF have been tested in in vitro settings where they were able to reduce growth of glioma cell lines, the migration of cells and arginase-1 assembly in MDSCs in a CXCR2-dependent manner." (PMID 38178143, 2024).
glioma (continued). "In glioma cell cytoplasm, overexpression of MIF suppressed DRP1 and p-DRP1 expression while enhancing OPA1 and MFN2 expression." (PMID 38405130, 2024). "Depletion of Arg1+ MDSCs via blocking migration inhibitory factor (MIF) or through a low-dose 5-flurouracil (5-FU) regime resulted in prolonged survival in a mouse model of glioma." (PMID 38464388, 2024). "In the mitochondria of glioma cells, MIF overexpression markedly inhibited DRP1 and p-DRP1 expression while increasing OPA1 levels, with no substantial impact on MFN2 expression." (PMID 38405130, 2024). "Studies have demonstrated that inhibition of the MIF/CD74 axis in gliomas will promote M1 phenotype polarization of microglia and exert anti-tumor effects." (PMID 38685050, 2024). "MSI1, a neural stem cell marker widely expressed in high-grade gliomas, is thought to be correlated with MIF and drives immunosuppression." (PMID 38732068, 2024). "In fact, MIF expression has been correlated with the severity of the disease, with high levels of MIF resulting in poor prognoses for glioma patients." (PMID 37046685, 2023). "Other than proteins such as MIF, glioma cells release certain RNA molecules such as microRNA-29a (miR-29a) and microRNA-92a (miR-92a), which have been implicated in the modulation of MDSC function." (PMID 37046685, 2023). "This was also observed in human glioma cells, in which the overexpression of MIF incremented the expression of mesenchymal markers." (PMID 36672343, 2023). "The fold changes of the MICB (p = 0.038) and MIF (p = 0.012) genes were observed to be lower in the glioma group relative to the control group." (PMID 34643804, 2022). "Circulating neutrophils are recruited at the tumor site by CXCL8 produced by FasL triggering on glioma cells or by the Migration Inhibitory Factor (MIF) produced by glioma cancer stem cells." (PMID 35440701, 2022). "The glioma groups with high MIF and DDT expression levels, respectively, had a poorer prognosis than the glioma groups with low expression levels." (PMID 34516577, 2021). "Macrophage migration inhibitory factor (MIF) exerts multimodal functions in glioma, including proliferation, migration, angiogenesis promotion, inhibition of apoptosis, and immune evasion properties." (PMID 34516577, 2021). "To analyze the clinical importance of MIF and DDT expression in gliomas, we first investigated the relationship of MIF and DDT expression with the survival of glioma patients using TCGA-GBMLGG cohort dataset (n = 694) from the UCSC Xena platform." (PMID 34516577, 2021). "The levels of MIF were found to be significantly elevated in gliomas compared to the normal brain, with levels correlating with glioma grade." (PMID 33803414, 2021). "Sulforaphane, a MIF inhibitor derived from broccoli sprouts, decreased levels of MDSCs in monocytes cultured with hypoxic glioma conditioned media." (PMID 33919732, 2021). "Glioma-derived macrophage migration inhibitory factor (MIF) also recruits MCs to glioma through signal transducer and activator of transcription 5 (STAT5) signaling in a malignancy-dependent manner." (PMID 34671362, 2021). "In two previous studies, brain tumor–initiating cells (BTICs) and glioma stem cells (GSCs) were shown to express higher levels of MIF compared with non–stem cells, and a correlation between MIF and stemness was demonstrated." (PMID 34516577, 2021). "In order to identify a potential targeted therapy that acts on the MIF/CD74 signaling axis and neutralizes M-MDSCs, we utilized the in vitro co-culture system to generate glioma educated MDSCS in the presence of different small molecule MIF inhibitors." (PMID 32625208, 2020). "The chemo-attractant macrophage migration inhibitory factor (MIF) produced by glioma stem cells also favor the recruitment of MDSCs, as well their functions through the regulation of ARG1 expression." (PMID 33374253, 2020).
glioma (continued). "In human gliomas, MIF is strongly expressed by tumor cells and its receptors CD74 is only restricted to microglial cells." (PMID 32903462, 2020). "Of note, a significantly positive correlation was observed between the number of MCs and the cytoplasmic intensity of MIF staining in glioma tissue samples." (PMID 30909395, 2019). "An earlier study has shown that MIF is highly expressed in human glioma cell lines which increases further with the grade of malignancy of human glioma patients." (PMID 31601918, 2019). "In particular, the accumulation of MCs, which is dependent on the malignancy grade of the glioma, correlates with the level of MIF expression." (PMID 29707160, 2018). "Inhibition of this glioma-microglial interaction through anti-MIF antibody or small interfering RNA (siRNA) treatment exerts beneficial effects in preclinical models by reinstating the microglial pro-inflammatory M1 function." (PMID 29707160, 2018). "An association has also been reported between elevated expression of MIF and tumor recurrence and poor prognosis of patients with gliomas." (PMID 29707160, 2018). "The results demonstrated that high-grade gliomas had more VM-positive specimens than did low-grade gliomas and that VM was closely associated with high co-expression of MIF and CXCR4 in gliomas." (PMID 29113309, 2017). "To confirm the presence of MIF in our glioma-conditioned media, we performed an ELISA with three separate biological replicates from our three glioma lines (BT114, BT116, BT120)." (PMID 28666020, 2017). "Immunochemical studies of specimens of glioma patients revealed that hypoxia-induced overexpression of MIF and CXCR4 co-localized with VM." (PMID 29113309, 2017). "We found that addition of anti-MIF blocking antibody blocks the formation of CD14+/HLA-DR- MDSC’s induced by glioma-conditioned media in our model system." (PMID 28666020, 2017). "ZEB1 is associated with malignancy in glioma and analysis of GBM patient specimens demonstrated that proinflammatory cytokines, such as CXCL12, IGFBP2, IL-1ß, TNF-a and MIF, correlate significantly with ZEB1 expression in tumor specimens." (PMID 28445977, 2017). "We have earlier shown that glioma derived macrophage migration inhibitory factor (MIF) is a potent chemoattractant for MCs." (PMID 26164207, 2015). "Previously we demonstrated that human glioma cells secrete a number of mediators among which MIF promotes human MC recruitment." (PMID 26164207, 2015). "We previously reported that SOX6 is highly expressed in human gliomas and that Macrophage migration inhibitory factor (MIF) supports the proliferation and/or survival of murine NSPCs in vitro." (PMID 24066135, 2013). "We therefore analyzed the growth of human glioma cell lines in vitro while targeting the MIF function in various ways." (PMID 20038293, 2009). "Analysis of the MIF mRNA expression under different cell densities of wildtype glioma cells, LN18 and LN229, revealed a marked difference between these cells." (PMID 20038293, 2009). "In line with other studies on the role of MIF in tumor biology, our data show a profound influence of MIF targeting on the proliferative response in human glioma cells." (PMID 20038293, 2009). "The expression of MIF has been described in tumours of the central nervous system and the potential role for tumour developement and progression in the brain has been recently reviewed." (PMID 20038293, 2009). "GBM exhibits marked upregulation of MIF expression compared to lower-grade gliomas." (PMID 41159021, 2025).
glioma (continued). "Notably, EIF3J-AS1 knockdown in METTL3-overexpressing glioma cells significantly rescued MIF expression." (PMID 41390674, 2025). "As a biomarker, MIF shows a complex relationship with glioma prognosis." (PMID 41159021, 2025). "Besides, the MIF/CD74 signaling inhibits the IFN-γ secretion by promoting ERK1/2 phosphorylation in glioma." (PMID 38685050, 2024). "Moreover, research has highlighted the potential of the exosome-mediated circWDR62 and macrophage migration inhibitory factor (MIF) in increasing TMZ resistance in glioma, suggesting their value as prognostic biomarkers." (PMID 38398214, 2024). "The investigation of posttranslational modifications in MIF in glioma requires further study." (PMID 38405130, 2024). "Treatment with 4-IPP (inhibitor of MIF or D-DT) showed the potential to improve radiotherapy by inhibiting the stemness and intracellular signaling pathways and inducing apoptosis in vitro and in vivo glioma models." (PMID 38178143, 2024). "Furthermore, the inhibition of macrophage migration inhibitory factor (MIF) derived by glioma cells was one of the mechanisms of sulforaphane’s ability to suppress MDSCs." (PMID 37375698, 2023). "A recent experimental study by Alban and colleagues has found that the monocytic subset of myeloid-derived suppressor cells (M-MDSCs) expresses high levels of CD74 in the presence of glioma-derived macrophage migration inhibitory factor (MIF) and glioma cells (Molecular event 5)." (PMID 36555253, 2022). "In addition to CCL2, the macrophage inhibitory factor (MIF) is secreted by glioma cells and regulates MDSCs recruitment into TME." (PMID 33919732, 2021). "In addition, the glioma group with both high MIF and DDT expression also had a poorer prognosis than the glioma group with low expression of both MIF and DDT." (PMID 34516577, 2021). "Recent studies have shown MIF could be used as a biomarker for poor prognosis in several cancers such as glioma, non-small lung cancer, and head and neck squamous cell carcinoma." (PMID 32943608, 2020). "MIF has demonstrated to be an appealing therapeutic target to reverse glioma-mediated MDSC buildup." (PMID 33204365, 2020). "Additionally, macrophage migration inhibitory factor (MIF) released by glioma cells contributes to the recruitment of MCs by inducing phosphorylation of STAT5." (PMID 31256327, 2020). "Furthermore, MIF expression is increased with glioma grade, and high levels of MIF in The Cancer Genome Atlas (TCGA) datasets correlate with a poor prognosis." (PMID 32625208, 2020). "In U87 and U251 glioma cell lines, high expression of MIF and CXCR4 promoted EMT and VM formation." (PMID 31993365, 2019). "We have observed that MIF is expressed in the four selected glioma cells and in this background, we hypothesized that MIF’s nuclease activity and AIF-mediated recruitment are required for AEBP1 down regulation induced parthanatos." (PMID 31601918, 2019). "Interruption of this glioma-microglial interaction through an antibody-neutralizing approach or small interfering RNA (siRNA)-mediated inhibition of MIF prolonged the survival time in glioma-implanted mice by reinstating the microglial pro-inflammatory M1 function." (PMID 30814573, 2019). "By taking advantage of a transwell migration assay, human glioma cell lines were shown to potently attract MCs by a mechanism partially dependent on the chemoattractant macrophage migration inhibitory factor (MIF), plasminogen activator inhibitor 1 (PAI-1) and the phosphorylation of STAT5." (PMID 30909395, 2019). "After verifying the correlation of HIF1α and MIF with CXCR4 in gliomas, we further explored whether hypoxia-induced high co-expression of MIF and CXCR4 was correlated with the formation of VMs." (PMID 29113309, 2017).
glioma (continued). "In our hands, differentiated human glioma cell lines also secreted abundant MIF." (PMID 28666020, 2017). "Furthermore, our previous studies have shown CXCL12 and MIF secreted from glioma cells to be potent chemoattractants for MC recruitment in glioma." (PMID 28445977, 2017). "Finally, to evaluate the clinical significance of MIF, CXCR4 and VMs in glioma, overall survival was analyzed by stratifying patients according to the immunochemistry score for MIF and CXCR4 or VM-positive." (PMID 29113309, 2017). "MIF, an abundant cytokine in three unique human glioma conditioned medias, may play a role in mMDSC formation as an MIF neutralizing antibody negates the effect of GCM on monocytes." (PMID 28666020, 2017). "A comprehensive understanding of the dynamics and hierarchy of MIF as a glioma-derived oncometabolite as well as immunological and vascular consequences is therefore critical in identifying effective drug targets in the development of multimodal managements of brain tumors." (PMID 22973314, 2012). "The aim of the study was to find out whether MIF plays a role in these altered growth processes in gliomas and also to test whether it might be a promising target for cancer therapy." (PMID 20038293, 2009). "We speculate whether METTL3 targets MIF through EIF3J-AS1 to inhibit autophagy in gliomas." (PMID 41390674, 2025). "Thus, it is possible to inhibit cancer cell growth by targeting DDT and MIF with a single molecule, which may provide more efficient therapeutic benefits to patients with glioma." (PMID 34516577, 2021). "Moreover, these antibodies successfully reduced, in a dose-dependent manner, the migration of MC cells, due to MIF blockade in the other glioma cell line U-2987 MG and diminish the CXCR2 mediated arginase-1 production, an immunosuppressive enzyme, in myeloid derived suppressor cells." (PMID 29707160, 2018). "However, in contrast to these numerous convergent findings on the detrimental role of MIF in favouring anti-tumour immune response another study has demonstrated that MIF receptor CD74 expression in human gliomas is restricted to microglia/macrophages and positively associated with patient survival." (PMID 29707160, 2018). "Thus, MIF is an attractive therapeutic target to reverse glioma-mediated MDSC accumulation." (PMID 28666020, 2017). "In addition, the decreased serum MIF level after tocilizumab injection might be another reason due to the tumor-promoting effects of MIF in gliomas." (PMID 27163161, 2016). "Collectively, these findings suggest that METTL3 suppresses MIF expression through EIF3J-AS1, thereby inhibiting autophagy in glioma cells." (PMID 41390674, 2025). "The pro-tumorigenic role of MIF in GBM is evident through its promotion of proliferation, migration, angiogenesis, and contribution to the immunosuppressive phenotype of glioma cells." (PMID 41159021, 2025). "Exosomal MIF enhanced tumour growth and TMZ obstruction of glioma cells in vivo, while IOS‐1 (an MIF inhibitor) significantly increased glioma sensitivity to TMZ in vivo." (PMID 39950738, 2025). "The JAM, APP, MIF, and NCAM signaling pathway networks were targeted by glioma cells, endothelial cells, astrocytes, and oligodendrocytes." (PMID 38824202, 2024). "Similar to the TCGA datasets, all 11 genes exhibited WHO grade-dependent expression in glioma samples, with 6 upregulated (LDHA, MIF, NAMPT, PGK1, SAT1, and PLOD2) and 5 downregulated genes (ALDOC, ABAT, ADCY2, GALNT13, and PDE8B)." (PMID 38989284, 2024). "Blockade of MIF with shRNA resulted in an increase of CD8-positive CTLs and reduction of Treg lymphocytes in the brain in animal models of glioma." (PMID 38178143, 2024). "The production of signaling factors (PNT, MIF, ANXA1, and MDK) in MAN1C1-expressing glioma cells enables communication with microglial/myeloid cell clusters." (PMID 39333557, 2024).